PGR (progesterone receptor)
Diseases named in the same sentence as PGR in open-access papers (continued):
Sharing a sentence is not in itself a finding about the gene and the disease.
tumor (continued). "However, hormone-related genes (BAG1, BCL2, CD68, ESR1 (ER), GSTM1, PGR, SCUBE2) do not show significant differential expression among all tumor samples." (PMID 38254834, 2024). "ER and PgR were negative, and the HER2 score was 1 + in all tumor areas." (PMID 37650999, 2023). "In contrast, an invasive, LN-positive triple-negative (lacking estrogen receptor (ER), progesterone receptor (PR) and human EGF receptor 2 (HER2)) breast tumor showed very light granular Plg-RKT staining of tumor cells and light to moderate staining of the reactive stroma." (PMID 35454092, 2022). "Among subgroups, the largest treatment benefit was observed in patients with high-grade tumor (HR, 0.322; 95% CI, 0.190–0.546), TFI < 36 months (HR, 0.418; 95% CI, 0.240–0.729), PgR status negative (HR, 0.427; 95% CI, 0.265–0.687), or presence of liver metastasis (HR, 0.449; 95% CI, 0.259–0.777)." (PMID 34158513, 2021). "Tumor cells were immunopositive for thyroid transcription factor 1 (TTF-1), Napsin-A and cytokeratin (CK)-7, and negative for paired box 8 (PAX-8), estrogen receptors (ER), progesterone receptor (PR) and CK20." (PMID 33853580, 2021). "Moreover, 40–85% of BC patients presented hypermethylation of the ESR1 gene that highly correlated with ER-negative/progesterone receptor (PR) negative conditions, suggesting that ESR1 methylation status strongly contributes to tumor phenotypes." (PMID 34863151, 2021). "In agreement with the gene expression data, mean protein levels of PgR increased between W1 and W2 or W3 (18.3% increase, p = 0.0015, FDR 0.024) but this did not lead to a change in PgR positive/negative status for any tumour." (PMID 31754627, 2019). "Examining the same genes in CCND1-amplified vs. non-amplified luminal A tumours showed increased MKI67 and decreased PGR gene expression in amplified tumours (see “MKI67” and “PGR”, P < 0.001 and P = 0.002 respectively), consistent with a more aggressive phenotype." (PMID 30819233, 2019). "Clinicopathological analysis showed that high ADORA2B expression has significantly reverse correlation with four important clinical parameters, ER positivity (P < 0.01), PgR positivity (P = 0.027), EGFR positivity (P < 0.01) and tumor size (P = 0.037), but not HER-2 positivity (P = 0.77)." (PMID 30349649, 2018). "Thus, the impact of TCC on RNA relative quantification is gene-specific and as far as MammaTyper® genes ERBB2, ESR1, PGR and MKI67 are concerned the bias introduced by the inclusion of tissue surrounding the invasive tumor appears to be non-critical." (PMID 30342538, 2018). "Additionally, the heterogeneity was not obvious in the meta-analysis of tumour size, tumour TNM stages, lymphovascular invasion and PgR status (I2 0–25.8%)." (PMID 29138453, 2017). "The prognostic features most commonly used in adjuvant treatment decision for node-negative patients include patient age, menopausal status, tumor size, tumor grade, Ki-67 score, HER2 status, and strength of estrogen receptor (ER)/progesterone receptor (PR) expression." (PMID 27081583, 2016). "In Prostatic stromal sarcoma (PSS) unlike the PES, immunohistochemically, the tumour cells are widely positive for vimentin, CD56, CD99 and focally positive for synaptophysin, CD10, progesterone receptor, desmin and CD34, but negative for EMA, cytokeratin, estrogen receptor, S-100 and myoglobin." (PMID 23886403, 2013). "Additionally, there are strong associations with both HER2 overexpressing and “triple negative” (ER−, progesterone receptor-negative, HER2−) tumor types and brain metastasis." (PMID 23346408, 2012).
tumor (continued). "All 11 ER negative tumours who achieved a pCR in the PET arm, were PgR negative too." (PMID 17047649, 2006). "Moreover, within the ERα-negative group of tumours, staining for AGR2 was positively correlated with staining for PgR." (PMID 16598187, 2006). "PS2 remained the strongest factor in multivariate analysis for PFS (P < 0.01) in this ER/PgR intermediate subgroup, but was not of predictive value in univariate or multivariate analysis for both PFS and PRS in tumours classified as ER/PgR low or high (> or = 75 fmol mg-1 protein)." (PMID 7981080, 1994). "Immunohistochemistry revealed the tumor cells were diffusely and strongly positive for both CK7 and E-cadherin (two blocks stained), positive for PAX-8 (nuclear staining), and negative for c-kit, vimentin, DOG-1, progesterone receptor (PR), carbonic anhydrase IX." (PMID 40018496, 2025). "Immunohistochemistry of the tumor confirmed the following: Glandular carcinoma: HER2 1+, estrogen receptor-negative, progesterone receptor (+,2%), and Ki-67 = 60%; Metaplastic carcinoma: HER2-negative, estrogen receptor-negative, progesterone receptor-negative, and Ki-67 = 40%." (PMID 36862895, 2023). "As evidenced by the best change in tumor size and corresponding ORR, all prognostic subgroups received benefit from the addition of abemaciclib to AI, with the largest effects observed in subgroups of patients with liver metastases, PgR-negative tumors, high-grade tumors, or TFI < 36 months." (PMID 34158513, 2021). "The tumor was biopsied via bronchoscopy and found to be a poorly differentiated carcinoma, which was strongly positive for cytokeratin 7 (CK7), carcinoembryonic antigen (CEA), and thyroid transcription factor-1 (TTF-1) but negative for CK20, estrogen receptor, and progesterone receptor." (PMID 29900025, 2017). "Furthermore, tumor cells were also positive for GCDFP15, ER, and PgR but negative for E-cadherin." (PMID 26199779, 2015). "The tumor in this case was an infiltrating solid, trabecular, and microglandular pattern and, in most ACC, the tumor cells were immunohistochemically positive for amylase, lysozyme, α1ACT, S-100 protein, and EMA but were negative for estrogen receptor, progesterone receptor, and HER2 protein." (PMID 24191209, 2013). "Furthermore, patients with ER-negative, progesterone receptor (PR)-negative and HER2-negative tumours (triple-negative, or basal-like cancers) lack an established therapeutic target and can only be treated with conventional chemotherapy (Linn and Van ‘t Veer, 2009)." (PMID 21119660, 2011). "Patients with PgR-positive tumours regardless of ER status (n=26) had the shortest median TTP (8.4 weeks), whereas patients with PgR-negative tumours had similar median TTP (15.4 weeks for ERnegative, PgR negative, n=60; 17 weeks for ER positive, PgR negative, n=12)." (PMID 19844234, 2009). "In the univariate analysis, tumor subgroup (TNBC vs. non-TNBC) was a significant factor related to 5-year overall survival, in addition to age, tumor size, lymph node, metastasis, grade, stage, estrogen receptor status, progesterone receptor status, and HER2 overexpression status." (PMID 19534825, 2009). "Hence, this study investigated the protein expression of ERα, ERβ, PGR, and AR in paired non-cancerous and cancerous tissues collected from patients diagnosed with CRC, and the results were analyzed according to gender, age, clinical stage, and tumor anatomical sites." (PMID 37206439, 2023).
tumor (continued). "Thus, experts commonly define three different BC subtypes: luminal-like (ER-positive and/or PgR-positive and HER2-negative), HER2-positive (HER2 overexpression/amplification, with any ER and PgR expression), and triple negative (ER-negative, PgR-negative and HER2-negative) tumours." (PMID 36900178, 2023). "However, unlike R-loop levels and tumour incidence, none of these abnormalities in BKO mice was rescued on further deletion of Cobra1 in DKO mice, nor were there any significant changes in levels of oestrogen receptor or progesterone receptor between BKO and DKO." (PMID 28649985, 2017).
cancer (628 papers, 1980 to 2026). A tumor composed of atypical neoplastic, often pleomorphic cells that invade other tissues. "In line with this notion, another study using all three—L1CAM, IMP3, and progesterone receptor (PR)—improved the diagnostic accuracy in preoperative endometrial samples compared to morphological assessment alone in detecting high-grade carcinomas." (PMID 40870967, 2025). "We apply these advances to construct a library of cancer-associated mutations in the ligand-binding domains of human estrogen receptor alpha and progesterone receptor to understand their impact on ligand-independent autoactivation." (PMID 38890276, 2024). "We identified cancer-associated nonsynonymous mutations in the LBDs of either ESR1 or PGR genes deposited in the cBioPortal for Cancer Genomics33,34." (PMID 38890276, 2024). "In contrast, in women, PgR expression in cancer cells was associated with poor prognosis, indicating that the significance of PgR expression in cancer cells and stroma is different." (PMID 37509283, 2023). "Steroid hormone receptors (SHRs), such as androgen receptor (AR), estrogen receptor (ER), and progesterone receptor (PR), are transcription factors associated with the development and involvement of many cancers." (PMID 36230806, 2022). "The final signature comprises five genes involved in proliferation (Ki-67, STK15, Survivin, CCNB1 and MYBL2), plus progesterone receptor (PR) and the cancer susceptibility gene GSTM1." (PMID 35567670, 2022). "In a comprehensive analysis of the large publicly available datasets, ERα(+)/PgR(−) tumors shared 5668 mutated genes with ERα(+)/PgR(+) cancers, while 1319 genes (19%) were uniquely altered in the former group." (PMID 34638241, 2021). "Mutations in ESR1, ESR2, and PGR genes were the most frequent alterations in multiple cancer types, followed by amplifications and deep deletions." (PMID 34322374, 2021). "Among the HER2(−) group of tumors, the ERα(+)/PgR(−) cases show significantly lower PGR mRNA expression when compared to ER(+)/PgR(+) cancers, suggesting that in most cases the loss of PgR occurs before or during transcription." (PMID 34638241, 2021). "To identify mutation sites in the ESR1, ESR2, and PGR genes, we assessed 10,189 samples from multiple cancer types." (PMID 34322374, 2021). "In a study of 107 post-menopausal patients receiving neoadjuvant exemestane for at least 4 months, pre-treatment PgR positivity > 50% was significantly associated with recurrence-free and cancer-specific survival." (PMID 32690069, 2020). "ER(+)/PgR(−) tumors tend to present less favorable clinicopathological features and a higher risk of relapse than ER+/PgR+ cancers." (PMID 32825530, 2020). "The mechanisms by which CYP1B1 polymorphisms increase cancer risk include enhanced estrogen and progesterone receptor signaling, also known to influence cancer treatment response." (PMID 33185690, 2020). "High-risk uterine factors were more common, and estrogen and progesterone receptor expression less common in NSMP subtype cancers of normal-weight patients compared with overweight/obese patients." (PMID 33232359, 2020). "Larger cancers (>2 cm) were more commonly associated with high Ki-67 (p < 0.001) and low PgR (p < 0.001)." (PMID 31975992, 2019). "One thousand two hundred twenty-four cases were included in our study as they met the diagnostic criteria of luminal type cancers which were estrogen receptor and progesterone receptor positive." (PMID 29291744, 2018). "A cancer-associated miRNA family, miR-200, was implicated in uterus of both human and mouse preterm labor and served as progesterone/progesterone receptor- (PR-) mediated regulators." (PMID 28713594, 2017). "It is possible that the information of progesterone receptor localization in cancers provided by this technique afford a specific diagnostic power over other techniques." (PMID 28415663, 2017).
cancer (continued). "High cyclin D1 expression was significantly associated to PgR positivity and lower grade and ER positivity when ER-positive and ER-negative cancers were tested together." (PMID 28528450, 2017). "In contrast, a case-control study from Japan reported that ever smoking was associated with an increased risk of PgR + cancer." (PMID 24516791, 2014). "Analysis of smoking-related measures revealed that starting to smoke at an early age of ≤19 years was significantly associated with an increased risk of postmenopausal ER-/PgR- cancer (odds ratio = 7.01, 95% confidence interval: 2.07-23.73)." (PMID 24516791, 2014). "On other hand, no smoking-related measure was found to be associated with the risk of ER+/PgR + cancer in either pre- or postmenopausal women." (PMID 24516791, 2014). "A recent cohort study from the US demonstrated a positive association between smoking and the risk of ER+/PgR + cancer among postmenopausal women." (PMID 24516791, 2014). "Although earlier reports on the association of PgR (+331G/A) polymorphism and cancer are inconsistent, the current meta-analysis has provided a definitive conclusion." (PMID 23349706, 2013). "For the association between PgR +331G/A polymorphism and cancer susceptibility, articles were retrieved based on the established search criteria." (PMID 23349706, 2013). "The PgR (+331G/A, rs10895068) promoter polymorphism is associated with cancer risk possibly by altering the expression of progesterone receptor B isoform." (PMID 23349706, 2013). "Similar to PARP-1-mediated regulation of transcription factor activity, PARP-1 plays a role in regulating three of the sex hormone receptors most commonly linked to cancer: estrogen receptor (ER), progesterone receptor (PR), and androgen receptor (AR)." (PMID 24350055, 2013). "We further explored this by examining PGR mRNA levels in these cancers and found that loss of PGR and IHH expression were correlated." (PMID 23785665, 2013). "Our meta-analysis identified an evident mild association between PgR (+331G/A) polymorphism and an increased cancer risk." (PMID 23349706, 2013). "A mild association between PgR +331G/A polymorphism and female reproductive cancer risk was detected." (PMID 23349706, 2013). "In contrast, our meta-analysis results revealed an association of the PgR (+331 G/A) polymorphism with a susceptibility to cancer." (PMID 23349706, 2013). "Early age of menarche increases the risk of ER/PgR-positive cancers, and a long interval between menarche and first birth increases the risk by 50 % in ER/PgR-positive cancers." (PMID 22711317, 2012). "Sex hormone receptors such as estrogen receptors (ERα and ERβ), progesterone receptor (PR) and androgen receptor (AR) are members of the hormone receptor family and have been associated with several human cancers, including breast, ovarian, prostate, colon, pancreas and hepatocellular carcinoma." (PMID 40868070, 2025). "However, there remain open questions to what extent endocrine interventions targeting ERα or the progesterone receptor further increase cancer risk in this subgroup." (PMID 38892081, 2024). "The presence of the estrogen receptor (ER), progesterone receptor (PR), and androgen receptor, which are linked to clinicopathological variables, may affect the prognosis among those with these cancers." (PMID 38523927, 2024). "These cell non-autonomous consequences of BRCA germline mutations potentially could be prevented by the administration of progesterone receptor antagonists such as mifepristone in women with a high lifetime genetic risk for these cancers." (PMID 35701800, 2022). "Furthermore, it was also inversely related to PgR (p = 0.0027) and its alterations were associated with G3 cancers (p < 0.0001)." (PMID 35745570, 2022). "While PgR-negativity assessed by IHC may be a technical issue, the other possibility is that alternative splicing of PgR produces cancer-specific variants of PgR that are undetectable with N-terminally targeting antibodies." (PMID 34638241, 2021).